Y_RNA (Y RNA )
Gene: Miscellaneous RNA gene on chromosome 20 (57,311,854 to 57,311,958, forward strand). Ensembl gene ENSG00000252064.
Homologues: Orthologues: chimpanzee Y_RNA (98% identical). Paralogues in human: Y_RNA (86% identical), RNY3 (85% identical), Y_RNA (85% identical), Y_RNA (84% identical), RNY3P14 (83% identical), Y_RNA (83% identical), RNY3P1 (82% identical), Y_RNA (82% identical), RNY3P4 (81% identical), Y_RNA (81% identical), RNY3P16 (80% identical), Y_RNA (80% identical), and 90 more.